IL1B (interleukin 1 beta)
Diseases named in the same sentence as IL1B in open-access papers (continued):
Sharing a sentence is not in itself a finding about the gene and the disease.
depression (continued). "Several mechanisms involved in spike protein have been proposed at the mice level such as TLR2-mediated depression, TLR4-mediated cognitive dysfunction, and anxiety mediated by non-cell autonomous hippocampal neuronal cell deaths by inducing IL-1β from glial cells." (PMID 38834668, 2024). "Therefore, it is possible that IL-1β is involved in the dysregulation of the HPA axis, which is one of the most robust biological markers of depression." (PMID 38791125, 2024). "Moreover, MCC950, an inhibitor of the NLRP3 inflammasome, has been shown to ameliorate depression‐like behavior in mice by suppressing the activation of NLRP3 inflammasome in the hippocampus and reducing the expression levels of NLRP3, ASC, and IL‐1β." (PMID 38970230, 2024). "In addition, XYS reduced the levels of IL-1β, IL-6, and TNF-α and increased the level of IL-10 in the sera of the mice with depression-like behaviors." (PMID 38378622, 2024). "The positive drug fluoxetine could also decrease NLRP3 and mature IL-1β levels, suggesting the inhibitory activity of neuroinflammation by PSP in CRS-induced depression." (PMID 39204578, 2024). "We also found significant evidence of differential effects by depression and pro-inflammatory cytokines such as IL-1β, IL-6 and TNF-α, in which the effects of D-50 (vs. placebo) were significantly greater among those with depression or elevated plasma concentrations of such cytokines." (PMID 39019875, 2024). "The increase of pro-inflammatory cytokines (interleukin (IL)-1β, IL-6, IL-18, and TNF-α) in individuals with depression may elicit neuroinflammatory processes and peripheral inflammation, mechanisms that, in turn, can contribute to gut microbiota dysbiosis." (PMID 38474387, 2024). "Furthermore, pro-inflammatory cytokines such as IL-1β and TNF-α have been reported to play an important role in the onset of depression, and an increase in pro-inflammatory cytokines contributes to the development of depression." (PMID 39057075, 2024). "At the cellular level, repercussions of these processes could be the production of IL-1α, IL-1β, TNF-α, and IL-6, as well as the activation of microglia and the impairment of astrocytes in depression." (PMID 36899845, 2023). "Consistently, the present study showed that MSD increased the expression levels of the proinflammatory factors IL-1β, IL-6, and TNF-α in the hippocampus, which may have contributed to the depression and cognitive dysfunction in the elderly offspring mice." (PMID 37168717, 2023). "For instance, TNF‐α, IL‐1β, IL‐6, and IL‐17A are elevated in coronary heart disease patients with anxiety and depression in comparison to those without these disorders." (PMID 37878890, 2023). "Furthermore, it has been shown that the serum levels of inflammatory cytokines such as interleukin- 1beta (IL-1β), IL-6, and tumor necrosis factor-alpha (TNF-α) are higher in individuals suffering from depression in compared to healthy people." (PMID 37151621, 2023). "Phase-I multiple regression analyses showed that young children exposed to high levels of socioeconomic disadvantage had higher salivary levels of TNF-α, IL-1β, and hair DHEA after adjusting for family dysfunction, caregivers’ depression, and anxiety levels (respectively)." (PMID 36650307, 2023). "Furthermore, we investigated the relationship between pro-inflammatory cytokines and depression by measuring the concentration of TNF-α, IL-6, and IL-1β in mice." (PMID 37173696, 2023). "We were not able to detect a concurrent contribution of IL-1β and IL-18 to the likelihood of depression, possibly because of their involvement in the NLRP3-independent pathways." (PMID 37763063, 2023). "Third, we determined that the concentrations of IL-1β, IL-6, DIO1, and DIO3 may influence the development of depression." (PMID 37834806, 2023). "These authors also found that IL-1β and TNF-α may be related with moderate depression symptoms in early pregnancy to midgestation." (PMID 37239199, 2023).
depression (continued). "Studies have reported that IL-6, TNF-α, CRP, YKL-40, IL-17, IL-1β, CCL2, IL-2, and IL‐8 are related to worse cognitive function or cognitive deterioration, while CRP, TNF-α, sIL-2R and CCL2 reflect severe symptoms of depression and anxiety." (PMID 36739284, 2023). "In the pain-depression dyad model, the AFIC-CDs groups decreased the immobile time, showed effect in increasing both the neurotransmitters’ levels and the expression of mRNA of BDNF and Tph2, and decreased the IL-1β and TNF-α levels in mouse brain cortex." (PMID 38259687, 2023). "Notably, ZSQGY was able to reduce the levels of IL-1β, IL-6, TNF-α, and IFN-γ, which demonstrated the anti-inflammatory effects of ZSQGY in the central nervous system in the MSG-induced depression model." (PMID 37251232, 2023). "This hypothesis was supported by meta-analyses showing that cytokine concentrations, including IL6, IL1β, IL17, and TNFα, were raised in the peripheral blood of patients with depression and anxiety compared with healthy controls." (PMID 37916198, 2023). "MSD has been found to activate the microglial cells and increase the expression levels of proinflammatory cytokines, including interleukin (IL)-1β, IL-6, and tumor necrosis factor-alpha (TNF-α), in the hippocampus, accompanied by depression and cognitive impairment." (PMID 37168717, 2023). "Moreover, the pro-inflammatory mediators IL-6, IL-1β, and TNF-α are elevated in diabetes-induced anxiety and depression." (PMID 38105928, 2023). "Plasma levels of IL-1β and IL-10 were not significantly different between depression patients and healthy controls." (PMID 37575572, 2023). "Despite being frequently dysregulated in inflammation-related disorders, IL-1β has not been consistently found increased in depression patients." (PMID 37575572, 2023). "Patients with depression disorder exhibit a chronic inflammatory state which is characterized by elevated serum levels of pro-inflammatory cytokines, including TNF-α, IL-1β, IL-2, IL-6, IL-12, and decreased levels of anti-inflammatory cytokines, such as IL-10, compared to controls." (PMID 37273278, 2023). "At present, the most consistent conclusion regarding the relationship between neuroinflammation and depression is that levels of proinflammatory cytokines; including TNF-α, IL-1β, and IL-6; are increased in both the plasma and central nervous system in patients suffering from MDD." (PMID 36909192, 2023). "Recently, it was shown that the treatment with the probiotic Bacillus coagulans Unique IS-2® reduced chronic stress-induced depression in rats by a mechanism related to an increase in BDNF and 5-HT levels and a decrease in TNF-α, IL-1β, and dopamine levels in the hippocampus and frontal cortex." (PMID 37892186, 2023). "It is therefore to be expected that FA and IL-1β correlate more negatively in people with depression than without depression." (PMID 36261698, 2022). "In addition, IL-1β secretion was closely controlled by the NLRP3 inflammasome, which plays an important role in the pathogenesis of depression." (PMID 35668399, 2022). "Baicalin significantly reduced the levels of TNF-α, IL-1β, and IL-6 in depression-like hippocampal tissues by upregulating PI3K/AKT/FOXO1 pathway and inhibiting TLR4 expression and so alleviate neuroinflammation-induced depression-like behavior." (PMID 35350754, 2022). "In addition, venlafaxine has been reported to play an anti-inflammatory role through downregulation of serum TNF-α, IL-1β, IL-6, and CRP in major depressive disorder and animal researches." (PMID 35664492, 2022). "Furthermore, serum corticosterone levels were markedly increased with IL-1β injection, while GR inhibitor RU486 reduced IL-1β-induced depression-like behavior and TNF-α and IL-6 expression." (PMID 36232376, 2022). "That means that the IL-1β concentration correlated more negatively in people with depression than without depression." (PMID 36261698, 2022).
depression (continued). "Similarly to manic episodes, serum levels of many inflammatory markers (CRP, TNF‐α, IL‐6, IL‐1β, sTNFR1, and CXCL10) are elevated during depressive episodes, and this alteration correlates with increased depression severity." (PMID 34590391, 2022). "COX-2 overexpression leads to an increase in the pro-inflammatory cytokines IL-1β, IL-6 and TNF, which increases the activity of the 5-HT transporter protein SERT, increases the affinity of the 5-HT receptor 5-HT1A, and mediates depression through an IDO mechanism that alters tryptophan metabolism." (PMID 36440427, 2022). "It has also been suggested that depression is an inflammatory disorder characterized by increased levels of proinflammatory cytokines such as tumor necrosis factor (TNF), interleukin-1β (IL-1β), and IL-6 in several brain regions, and similar findings have been reported in experimental studies." (PMID 36185078, 2022). "The result of one human study showed a higher blood level of IL-1β in epilepsy with depression compared with that without depression." (PMID 35504954, 2022). "Proinflammatory cytokines (IL-1β, IL-6 and TNF-α) may be screening biomarkers in the prediction of treatment response in patients with depression." (PMID 36350802, 2022). "In addition, there was significant increase of serum corticosterone and IL-1β, as well as higher levels of NLRP3 protein in hippocampus in the chronic stress-induced depression mice models." (PMID 35496273, 2022). "In this study, we found that the CMS protocol increased Iba1 expression as well as TNF-α, IL-1α, and IL-1β levels in the hippocampus or serum, while MOs successfully inhibited this effect in CMS-exposed mice, leading to the attenuation of depression-like symptoms." (PMID 36052143, 2022). "It was shown that dimethyl fumarate can reduce IL-1β, IL-18, caspase-1, and NLRP3 levels through the Nrf2/NF-κB signaling pathway, thus inhibiting LPS-induced microglial pyroptosis and disease manifestations in LPS-challenged depression mice." (PMID 35722622, 2022). "In this sense, the greater the depression in patients with PD, the higher the state and trait anxiety, the perceived stress, the GI symptoms, the reactivity of the HPA axis and the lower the levels of IFN‐γ, IL‐1β, and IL‐12." (PMID 35588458, 2022). "Interestingly, we observed the characteristic hallmarks of pyroptosis in depression, which included increased activation of NLRP3 inflammasome and the release of IL-1β and IL-18." (PMID 35496273, 2022). "We also examined the mRNA level of inflammation-related factors, including IL-1β, IL-6, TNFα, and IL-10 in the PFC, dorsal hippocampus, and ventral hippocampus, which are three critical regions of the brain that are related to anxiety and depression." (PMID 35684068, 2022). "Besides, other studies evaluated the IL-1β, TNF-α, and IL-6, and showed that they are overexpressed in patients with depression." (PMID 35496273, 2022). "It is suggested that muscone may alleviate IL-1β-related CNS inflammation through TLR4/MyD88 and TLR4/NLRP3 pathways, thereby attenuating LPS-induced depression-like behaviors." (PMID 35923544, 2022). "Proinflammatory cytokines, such as IL-1β, IL-6, and TNF-α, might play crucial roles in the pathophysiology and treatment of depression." (PMID 35496318, 2022). "To investigate the differences in the expression of inflammatory factors in the serum of normal person, patients with depression, and patients with DCMI, we performed ELISA to detect the levels of NPY, T, IL-1β, IL-6, TNF-α, IL-10, and IL-4 in the peripheral blood plasma." (PMID 35432561, 2022). "In addition, BHB induction attenuated expression of IL-18, IL-1β and NLRP3 inflammasome in a rodent model of depression." (PMID 36533180, 2022).
depression (continued). "Animal research also showed that treatment with agomelatine reversed the signs of anxiety and depression, and decreased the cytokines (tumor necrosis factor-α [TNF-α], interleukin 6 [IL-6], and IL-1β), thiobarbituric acid reactive substances, as well as caspase-3 activity." (PMID 34079622, 2021). "Therefore, there have been calls for peripheral blood IL-1β, IL-6, and TNF as biomarkers of depression patients." (PMID 34650925, 2021). "Animal experiments have shown that IL-1β in the brain can mediate chronic stress-induced depression-like behaviors, while IL-1β receptor knockout mice will not show depression-like behaviors after stress." (PMID 34054732, 2021). "Notably, increased levels of pro-inflammatory cytokines such as IL-1β, IL-6 and TNF-α were markedly decreased in patients with depression receiving antidepressant treatment." (PMID 34889698, 2021). "Excessive secretion of IL-1β, IL-6, and TNF-α triggers depression-like symptoms." (PMID 33584387, 2021). "Increased IL-1β, IL-10 and TNF levels are present in patients with depression." (PMID 34610039, 2021). "Depression severity was not significantly correlated with IL1β levels both in lysates and plasma at both T0 and T1." (PMID 35002816, 2021). "However, other studies have reported that the concentrations of IL-1β, IL-6 and/or CRP in the serum or cerebrospinal fluid were positively correlated with depression severity only, or more profoundly in females." (PMID 33672958, 2021). "In the cotreatment model, giving memantine concomitantly during the paclitaxel treatment led to a potentially better suppression of peripheral TNF-α and IL-1β and tissue TNF-α expression, thus leading to a better reversal of mood symptoms and prevention of depression-like behavior." (PMID 34439331, 2021). "Notably, increased peripheral levels of IL-1β, and of IL-1β and IL-6, but unchanged TNF-α, were reported in patients with AD or major depression, respectively." (PMID 34109176, 2021). "IL-1β activates the HPA axis and induces depression-like behavior in rats." (PMID 34526897, 2021). "The proinflammatory IL-1β and TNF-α cytokines could also interfere with the brain and lead to decreased appetite, sleep disturbance, and depression." (PMID 34200732, 2021). "However, orally gavaged or intraperitoneally injected buspirone significantly reduced EC-induced anxiety-/depression-like behaviors, suppressed EC-induced TNF-α and IL-1β expression in the hippocampus." (PMID 33731795, 2021). "Depression-like behavior and hippocampal neuroinflammation in CUMS model rats were manifested by down-regulated expression of α7nAchR, up-regulated expression of NF-κB p65 and IL-1β, and the morphology of microglia was in amoebic-like activated state." (PMID 34920740, 2021). "Due to the multifaceted pathogenesis of depression, this study aimed to clarify whether the KBD formula ameliorated the effect of UCMS-induced changes in expression levels of the depression-related genes BDNF, CREB, GR, SGK1, FKBP5, IL-1β, IL-6, and TNF-α." (PMID 34358084, 2021). "Most of the inflammatory markers involved in Psoriasis (TNF-α, IL-2, IL-6, IL-23, IL-1β, IL-10), and increased serotonin transporters (5-HTT) were also found in the pathogenesis of depression, showing the immune-inflammatory linkage between psoriasis and major depression." (PMID 34183985, 2021). "Cerebral ischaemia leads to the production of increased proinflammatory IL-1β and TNF-α, which could further result in decreased 5-HT production, additionally promoting depression." (PMID 32184899, 2020). "The expression levels of NLRP3 inflammasome mRNA and IL-1β are significantly increased in the brains of depressed mice induced by lipopolysaccharide (LPS), suggesting that IL-1β and NLRP3 inflammasome are the mediators of inflammation between stress and depression." (PMID 32166013, 2020). "Furthermore, the levels of IL-1β, IL-6, TNF-α, and TGF-β are positively correlated with the symptoms of depression." (PMID 33613190, 2020).
depression (continued). "Based on these reports, it was suggested that peripheral blood IL-1β, IL-6, TNF, and CRP could constitute reliable biomarkers of inflammation in patients with depression." (PMID 32380663, 2020). "Bivariate Pearson’s correlations table between IL-6 and IL-1β with childhood trauma experiences, psychological outcomes, and physical outcomes among participants with and without clinically significant depression." (PMID 32413063, 2020). "Moreover, increased expression of various innate immune genes, including IL-1β, IL-6, TNF, TLR3, and TLR4, have been found in post-mortem brain samples from suicide victims that had depression." (PMID 32380663, 2020). "Finally, the attenuation of gut dysbiosis and IL-1β expression by beneficial bacteria, including NK109, can alleviate neuropsychiatric disorders such as cognitive impairment and depression." (PMID 33182607, 2020). "IL-1β, IL-6, and TNF-α are the most generally demonstrated proinflammatory cytokines in depression." (PMID 32596383, 2020). "Importantly, it has been reported that the pro-inflammatory cytokine IL-1β can regulate the trafficking of AMPA receptors, leading to depression-like behaviors in mice after chronic social defeat stress (CSDS)." (PMID 32635937, 2020). "NK109 significantly alleviated Escherichia coli K1-induced cognitive impairment- and depression-like behaviors in germ-free and SPF mice by regulating the immune response through NF-κB-involved BDNF expression, IL-1β expression, and vagus nerve-mediated gut–brain signaling." (PMID 33182607, 2020). "In in vitro and in vivo models of depression, BDNF was shown to improve depressive-like behavior by upregulating anti-inflammatory cytokine IL-10, IL-4, and TGF-β1 and downregulating the pro-inflammatory cytokine IL-1β, IL-17, and TNF-α." (PMID 32256638, 2020). "Astrocyte activation could result in the release of inflammatory cytokines, including IL-1β, IL-6, and TNF-α, which could promote the symptoms of depression." (PMID 32321532, 2020). "Moreover, patients with a history of recurrent depression have greater peripheral levels of IL33 and IL1B." (PMID 30306457, 2019). "We therefore examined the effects of Aβ1-42 oligomers i.c.v. injection on the mRNA levels of pro-inflammatory cytokines (IL-1β and TNF-α) and anti-inflammatory cytokines (IL-4 and TGF-β1) in the hippocampus, a brain area of primary relevance in the pathogenesis of depression." (PMID 31293421, 2019). "Cytokine profiles for different animal models of depression indicates that various forms of stress exposure induces the release of pro-inflammatory cytokines such as INF-γ, IL-1β, and IL-6, which implicates immune responses as an underlying mechanism of depression caused by stress." (PMID 31312123, 2019). "Similarly, IL1B and IL18 are increased in MDD, and their levels correlate with the severity of depression." (PMID 30306457, 2019). "It was found that SNS may up-regulate CYP1A2, CYP2D1, CYP2E1, and CYP3A2 activity to reduce IL-6 and TNF-α expression, as well as up-regulation of BDNF and its receptor TrkB, reduce IL-1β, IL-6, and TNF-α expression to treat depression." (PMID 32009949, 2019). "In addition, the expression of IL-1β, IL-6, and TNF-α was also increased in postmortem brain samples from suicide victims that suffered from depression." (PMID 31068207, 2019). "However, the involvement of IL-1β has not been as consistently linked to depression, possibly owing to difficulties in detecting this cytokine in blood samples or that changes in circulating levels might only be apparent in a subgroup of patients who have experienced early-life adversity." (PMID 30967802, 2019). "Interestingly, ROS seems to activate ABL1/NF-κB1-related cytokines (IL-6, IL-1β, and COX2), thus involving itself in the process of depression." (PMID 31396300, 2019).